BRCA1 (BRCA1 DNA repair associated)
Diseases named in the same sentence as BRCA1 in open-access papers (continued):
Sharing a sentence is not in itself a finding about the gene and the disease.
breast tumors (continued). "Strikingly enough BRCA1 vs BRCA2 tumours also showed significant differences in PPI distributions (KS test: DB12 = 22.85 > Kα = 0.05 = 1.36), reflecting considerable differences in PPI wiring between the two breast tumours." (PMID 25521701, 2014). "The histopathologic characteristics of BRCA1 and BRCA2 breast tumors are well described." (PMID 24479546, 2014). "In summary, our immunohistological studies of frozen and FFPE tissues of breast tumors with monoclonal antibodies MS110 and AP16 and the polyclonal antibody K-18, with immunoperoxidase and immunofluorescence detection, have shown that BRCA1 protein has a nuclear and nucleolar localization." (PMID 23855721, 2013). "In some of our samples, we found less positive BRCA1 nuclear staining in FFPE breast tumor tissue compared to normal tissue as in this example from patient no.19.We also found strongly stained normal tissue in specimens nos." (PMID 23855721, 2013). "The differences in staining between frozen and FFPE sections based on a varied group of infiltrating breast tumors, suggest that the sub-nuclear localization of BRCA1 is best studied by comparison of frozen and FFPE sections, using an array of BRCA1 antibodies, and fixation procedures." (PMID 23855721, 2013). "Fifty seven percent of breast tumours revealed absent (15% ) or reduced (42% ) nuclear expression of BRCA1,while 43% of the cases showed strong nuclear expression." (PMID 23508738, 2011). "Our results indicate that BRCA1 is methylated at both K and R residues (lanes 1–4) in all four breast tumor patient samples, while no methylation was observed with the negative control IgG IP (lane 5)." (PMID 20614009, 2010). "53BP1 expression was recently found frequently decreased in a subset of basal-like/triple-negative breast cancers and in BRCA1 or BRCA2 negative breast tumors." (PMID 21054854, 2010). "The study group consisted of 67 primary breast tumours with and without BRCA1 or BRCA2 abnormalities." (PMID 19589159, 2009). "Breast tumours arising in these conditional Bard1- and/or Brca1-mutant mice were indistinguishable from each other." (PMID 19904273, 2009). "We then specifically addressed the question of whether the BRCA1 and BRCA2 genes are involved in sporadic breast tumour development." (PMID 19589159, 2009). "Not surprisingly, BRCA1 expression levels in normal breast tissue were significantly higher those seen in sporadic breast tumors (p = 0.01)." (PMID 17511879, 2007). "The expression levels of BRCA1 and the PP1 isoforms were analyzed in primary human breast tumors." (PMID 17511879, 2007). "AI at the BRCA1 and BRCA2 loci are know to be relatively common in breast tumours." (PMID 16846527, 2006). "Interestingly, there is a nine-fold decreased expression of SFN in BRCA1- and BRCA2-related tumours compared to sporadic breast tumours." (PMID 16280053, 2005). "Given the functional implications of BRCA1 inactivation on the translation of ADAT2, CCNL2, DBF4B, and TRIM45, we wondered whether the levels of these proteins were correlated to BRCA1 status in breast tumors." (PMID 32290274, 2020). "Triple‐negative breast cancer (TNBC) tends to have a very high STC1 level compared to normal tissues, and ER‐positive tumours also possess a relatively higher STC1 expression level than normal, whereas STC1 may be absent in BRCA1‐mutant breast tumours." (PMID 32468698, 2020).
breast tumors (continued). "In the present study, miRNA expression profiles were analyzed in a series of hereditary breast tumors (BRCA1/2 and BRCAX-associated breast tumors), sporadic breast tumors and NBT from BRCA1/2-germline mutation carriers and non-carriers using NanoString nCounter Technology." (PMID 32087690, 2020). "A possible mechanism is that the ZNF350/BRCA1/CtTB-interacting protein complex represses the expression of angiopoietin-1 (ANG1) and high-mobility group AT-hook 2 (HMGA2), which are commonly involved in the proliferation and vascularization during breast tumor formation." (PMID 30613364, 2018). "In comparison with breast tumours associated with other BC susceptibility genes, we thus confirm previous observations showing that ATM-associated tumours do not resemble BRCA1-associated tumours or PALB2-associated tumours, which are also predominantly triple-negative tumours." (PMID 29665859, 2018). "When tumors were stratified by mutation and tumor type, the means of these three scores (HRD-Mean) were significantly higher in BRCA1 and BRCA2 germline mutation-associated breast vs. nonBRCA breast tumors, and between BRCA1 germline mutation-associated and nonBRCA ovarian tumors." (PMID 28831036, 2017). "Notably, the calculated BRCA scores using the BRCA1/2-based profile achieved the best classification accuracy when comparing familial breast tumors from sporadic ones (right, AUC = 0.861 for BRCA1 vs. sporadic, ACU = 0.809 for BRCA2 vs. sporadic and AUC = 0.84 for BRCA1/2 vs. sporadic)." (PMID 29146938, 2017). "Constitutive AhR expression coupled to BRCA-1 promoter CpG hypermethylation may be predictive markers of ERα-negative breast tumor development." (PMID 26715507, 2015). "Therefore, AhR-dependent repression of BRCA-1 via increased CpG methylation may disrupt this positive feedback loop between BRCA-1 and ERα and favor the development of ERα- and BRCA-1-negative breast tumors." (PMID 26715507, 2015). "Even within breast tumors, the accepted combination of surface markers CD44/CD24 shows differences among different subtypes, being the CD44+/CD24− phenotype common in the basal subtype, specially in BRCA1 hereditary tumors, but surprisingly scarce in HER2-positive tumors." (PMID 25414831, 2014). "This study has shown no overlap between two cell populations, suggesting that breast tumours may exhibit inter-tumour cell heterogenicity in BRCA1 tumours which may result from different cells of origin." (PMID 23508738, 2011). "Blinded pathology review of 35 tumors from cases who carried a likely deleterious ATM variant and a hospital-based series of 38 age-matched control breast tumors did not reveal any distinctive pattern of histopathologic characteristics, as had been previously reported in BRCA1 tumors." (PMID 21787400, 2011). "Moreover, we show that global heterochromatin defects observed in breast tumor cells are independent of BRCA1 status." (PMID 19440381, 2009). "The major component of around 20% of the breast tumors was not Age, APOBEC, or BRCA1/2 signatures but distributed across other signatures." (PMID 31294536, 2019). "Whereas to human and mouse breast tumor cells tested, the PARP1 inhibitors were either ineffective or eliminate these cells irrespective of BRCA1 status." (PMID 29069872, 2017). "None of these features is, however, unique and therefore none can be used to distinguish BRCA1 and BRCA2 tumors from sporadic breast tumors." (PMID 23704984, 2013). "Our observation followed by statistical analysis of methylation status in breast tumors along with transcript expression revealed a negative correlation for TRAIL, DR4, CASP8, ATM, CHEK2, BRCA1 and BRCA2 CpG sites." (PMID 21092294, 2010).
breast tumors (continued). "However, miRNAs validated by quantitative polymerase chain reaction (qPCR) (miR-4417 and miR-423-3p) could only discriminate hereditary (BRCA1, BRCA2, and BRCAX) from non-hereditary breast tumors (70.1% accuracy)." (PMID 32087690, 2020).
triple-negative breast carcinoma (495 papers, 2008 to 2026). An invasive breast carcinoma which is negative for expression of estrogen receptor (ER), progesterone receptor (PR), and human epidermal growth factor receptor 2 (HER2). "The tumor cells and compared normal luminal cells were obtained from a triple-negative breast cancer patient (case #3) carrying a BRCA1 germline mutation." (PMID 41498327, 2026). "While inherited BRCA1/BRCA2 mutations drive hereditary risk, recent evidence highlights the critical role of BRCA1 promoter methylation especially in sporadic and triple-negative breast cancers (TNBC), which disproportionately affect African-descended women." (PMID 41836332, 2026). "Pathogenic variants (PVs) in BRCA1/2 in patients with ovarian and triple-negative breast cancer (TNBC) were extensively studied in the Western population." (PMID 40714512, 2025). "Unlike BRCA2 mutation carriers, who are more likely to develop tumors that are progesterone receptor (PR)- or estrogen receptor (ER)-positive, BRCA1 mutation carriers predominantly develop triple-negative breast cancer (TNBC)." (PMID 39997609, 2025). "In preoperative chemotherapy for triple-negative breast cancer, homologous recombination deficiency not limited to BRCA1/2 mutations showed high response rates to platinum-based chemotherapy." (PMID 40557004, 2025). "This is also supported by prior work showing upregulation of type I IFN in a PDX model of Brca2 WT triple-negative breast cancer at higher olaparib doses than in a BRCA1-mutated PDX model." (PMID 40579444, 2025). "In line with this, RAD50 mutations compromise the functionality of BRCA1, causing an accumulation of unrepaired lesions and promoting more aggressive subtypes, such as triple-negative breast cancer." (PMID 40282418, 2025). "Suppose women have a history of unmarried and childless, family inheritance, triple-negative breast cancer, postoperative oral selective estrogen antagonist, and BRCA1/BRCA2 gene mutation." (PMID 40530017, 2025). "This case reports a patient with a BRCA1 mutation who developed multiple malignancies, including cervical cancer and recurrent triple-negative breast cancer (TNBC)." (PMID 40949480, 2025). "Constitutional BRCA1 epimutations (promoter hypermethylation) are associated with an elevated risk of triple-negative breast cancer and high-grade serous ovarian cancer." (PMID 39980037, 2025). "With the positive outcome on progression-free survival, olaparib has been further evaluated in Phase III clinical trials in combination with cisplatin/carboplatin with gemcitabine in BRCA1-associated and triple-negative breast cancers." (PMID 41155174, 2025). "In Saudi Arabia, a recent study identified constitutional BRCA1 promoter methylation as being significantly associated with triple-negative breast cancer, underscoring potential genetic predisposition." (PMID 41228196, 2025). "The co-occurrence of recurrent triple-negative breast cancer and cervical cancer in a patient with a BRCA1 mutation underscores the importance of genetic factors in the development of multiple primary malignancies." (PMID 40949480, 2025). "About 20% of patients with triple-negative breast cancer present mutation in the BRCA1 or BRCA2 genes, which are essential to the repair of double-strand DNA breaks by homologous recombination repair." (PMID 38506114, 2024). "Somatic mutations in BRCA1 are more commonly associated with basal-like and triple-negative breast cancers, while somatic BRCA2 mutations can lead to various subtypes, including luminal and TNBC." (PMID 39272660, 2024). "In the triple-negative breast cancer subgroup, the BRCA1/2 double mutation frequency was 0.06% (1/1773), and the BRCA1/2 and PALB2 triple mutation frequency was 0.06% (1/1773)." (PMID 38439896, 2024). "The BRCA1 c.3607C>T mutation, though less common in Romania, was mainly linked to triple-negative breast cancer and ovarian serous adenocarcinoma." (PMID 39272683, 2024).
triple-negative breast carcinoma (continued). "The platinum-based therapy of BRCA1 methylated triple negative breast cancer patients resulted in allelic loss of BRCA1 methylation, increased BRCA1 expression, and platinum resistance." (PMID 39769312, 2024). "In Group I-D (single case of triple-negative breast cancer diagnosed ≤ 50 years old), we detected a high probability of finding pathogenic variants in BRCA1/2 genes." (PMID 39438962, 2024). "The example data provided with the notebook includes quantitative values for three cell lines including MCF10A (normal epithelial), MDA-MB-231 (triple negative breast cancer), and HCC1937 (triple negative breast cancer with BRCA1 mutation)." (PMID 39041914, 2024). "We examined the tumor growth inhibition properties of PLX038A on BRCA1-deficient MDA-MB-436 triple negative breast cancer (TNBC) xenografts." (PMID 38898077, 2024). "Patients with triple-negative breast cancer (TNBC) are candidates for PARP inhibitors if they have BRCA1 or BRCA2 mutations." (PMID 39685105, 2024). "Pathogenic germline BRCA1 mutations (gBRCA1m) predispose women to breast cancer, especially triple-negative breast cancer (TNBC)." (PMID 38191387, 2024). "A single-arm prospective study using cisplatin monotherapy in the neoadjuvant setting reported a pathologic complete response rate of 61% among BRCA carriers, most of whom had BRCA1 mutations and triple-negative breast cancer." (PMID 39238026, 2024). "Triple-negative breast cancer (TNBC) patients are more likely to have BRCA1/2 mutations, with a prevalence rate of about 10–20%." (PMID 38689097, 2024). "Another potential strategy is the combination of a PARPi with anti-CSF-1R, as it was shown to overcome resistance in BRCA1-deficient triple-negative breast cancer." (PMID 38236558, 2024). "Triple-negative breast cancer is more common in people with BRCA1 gene mutation, younger women, and black women." (PMID 38672654, 2024). "For example, BRCA1 promoter methylation indicates PARPi resistance of triple-negative breast cancer cells, which makes germline BRCA1 mutations the most reliable biomarkers in predicting tumor response to the PARPi-based therapies." (PMID 37108815, 2023). "Consistent with this, loss of ISG15 has dramatic effects on cell fitness, impairing proliferation of BRCA1-mutated triple-negative breast cancer cells." (PMID 37783689, 2023). "In particular, subsets of certain cancers, such as triple-negative breast cancer (10–15%) and castration-resistant prostate cancer (13.6%), have a higher prevalence of BRCA1/2 mutations than does the whole population of that cancer." (PMID 38069409, 2023). "Normal cell BRCA1 epimutations have been associated with increased risk of triple-negative breast cancer (TNBC)." (PMID 38053165, 2023). "ACMG classification identified 7% of patients harboring Pathogenic/Likely Pathogenic (P/LP) variants, with one case displaying a pathogenic BRCA1 mutation linked to triple-negative breast cancer (TNBC)." (PMID 38028594, 2023). "The frequency of pathogenic variants in women with triple negative breast cancer was 23.2%, with 91% of the observed pathogenic variants detected in BRCA1, BRCA2, and PALB2." (PMID 36544278, 2023). "The highest ORR was observed in the triple-negative breast cancer (TNBC) arm (patients with BRCA1/2 mutations and/or homologous recombination deficiency) (ORR: 47.4%; median DoR: 17.1 months [95% CI: 3.0, NE])." (PMID 37474720, 2023). "One possible explanation is that patients with BRCA1 mutations are more likely to have triple-negative breast cancer, which is associated with a higher risk of distant recurrence." (PMID 38098088, 2023).
triple-negative breast carcinoma (continued). "A siRNA screen targeting F-box proteins by Michele Pagano's group showed that downregulation of EMI1/FBXO5 in BRCA1-deficient triple-negative breast cancer (TNBC) cells conferred PARPi resistance." (PMID 37609662, 2023). "Preclinical studies show that expression of functional BRCA1 protein in patient-derived xenograft (PDX) models of BRCA1-methylated triple-negative breast cancer can be mediated by BRCA1 hypermethylation loss." (PMID 37569269, 2023). "This possibility has been best studied in germline BRCA1-associated tumours, a related tumour suppressor gene whose inactivation predisposes women to triple-negative breast cancer subtypes." (PMID 37626143, 2023). "Several cases of m6A methylated modification in cancer have been reported in the literature, and it is clear that the variant rs8100241 located in ANKLE1 was significantly associated with susceptibility of BRCA1 mutation triple negative breast cancer." (PMID 37194014, 2023). "For example, in triple-negative breast cancer, the frequency of mutations in the BRCA1 gene is up to 16%." (PMID 37628606, 2023). "PARP-1 (nuclear) expression and BRCA1 mutations were mainly detected in triple negative breast cancer patients, and the latter were correlated with decreased survival." (PMID 35406503, 2022). "It is very important that our study also identified novel frameshift variant, c.5485delG in BRCA1, which was found in first diagnosed at 28 years old as metachronous bilateral triple negative breast cancer patient with unilateral medullary carcinoma." (PMID 36324133, 2022). "In contrast, BRCA1 mutations tended to have higher occurrence rate among patients with triple-negative breast cancer." (PMID 35494038, 2022). "The basal-like type lacking hormone receptors and overexpressing HER2 is often considered triple-negative breast cancer, which can only be treated with chemotherapy, and is more common in patients with BRCA1 mutations or African ancestry." (PMID 36446386, 2022). "Carriers of BRCA1 mutation are more likely to develop triple-negative breast cancer (TNBC), which suggests that BRCA1 mutation and the hormone receptor status are interlinked." (PMID 35300412, 2022). "Just as BRCA1 mutation is more common in triple negative breast cancer, whereas BRCA2 mutations are more common in Luminal B breast cancer." (PMID 35509067, 2022). "Many studies around the world have indicated the presence of an association between BRCA1/2 genetic alterations and the sporadic form of triple-negative breast cancer (TNBC) and high-grade serous ovarian carcinomas (HGSC)." (PMID 35986351, 2022). "This study aims to reveal the molecular mechanisms and therapeutic relevance of BRCA1 L1780P mutation in DNA damaging response of triple-negative breast cancer (TNBC)." (PMID 35626017, 2022). "The majority of triple-negative breast cancer (TNBC) patients are young women with a BRCA1 gene mutation." (PMID 35744786, 2022). "We also assessed CB-5083 in combination with PARPi in a patient-derived organoid culture derived from a patient with triple-negative breast cancer harbouring a germline pathogenic BRCA1 p.R1203* mutation (BRCA1 c.3607C>T), which was homozygous in the organoid." (PMID 35013556, 2022). "Knocking out BRCA1 in triple-negative breast cancer cell lines causes hypersensitivity to the OGG1 inhibitor TH5487." (PMID 35619904, 2022). "For instance, genetic testing for germline BRCA1/2 mutations has evolved to be a part of the standard clinical practice in patients with triple negative breast cancer (TNBC)." (PMID 35494038, 2022). "In BRCA1-deficient triple-negative breast cancer (TNBC) cells, PARP3 inhibition exacerbates centrosome amplification and genome instability via limitation of Rictor protein level by ubiquitination, thus efficiently represses oncogenic Rictor/mTORC2 signaling." (PMID 35982899, 2022).